SDHB (succinate dehydrogenase complex iron sulfur subunit B)
Diseases named in the same sentence as SDHB in open-access papers (continued):
Sharing a sentence is not in itself a finding about the gene and the disease.
metastatic disease (continued). "Out of all SDHx mutation carriers, patients with an SDHB mutation carry the highest risk for metastatic disease." (PMID 35158861, 2022). "The five-year overall survival ranges from 50% to 70% The risk factors for metastatic disease additionally to germline SDHB-mutation comprise of noradrenergic or dopaminergic phenotype, size (>5 cm), and extra-adrenal location." (PMID 35163370, 2022). "It is well established that mutations in succinate dehydrogenase B (SDHB) are associated with high risk of metastatic disease." (PMID 35201450, 2021). "SDHB mutations are strongly associated with extra-adrenal sympathetic paragangliomas with an increased risk of metastatic disease, and less frequently, with Pheos and parasympathetic PGLs." (PMID 34181326, 2021). "PPGLs in this cluster are mainly extra-adrenal and aggressive, and particularly those related to SDHB mutations, are associated with the highest proportion of metastatic disease." (PMID 34201922, 2021). "In conclusion, patients with SDHB-mutated PHEO/PGL have a higher likelihood of metastatic disease with limited therapeutic options and poor prognosis." (PMID 34359671, 2021). "Patients with SDH subunit B (SDHB)-mutated PHEO/PGL exhibit a higher likelihood of developing metastatic disease, which can be partially explained by the metabolic cell reprogramming and redox imbalance caused by the mutation." (PMID 34359671, 2021). "SDHB mutations are especially related to sporadic malignant Pheo with poor prognosis, and up to 40% of patients with metastatic disease harbor mutations in this gene." (PMID 34181326, 2021). "SDHB gene was reported to confer a higher risk of malignancy, but only half of patients with metastatic disease carried inherited SDHB mutations." (PMID 34069252, 2021). "PPGL are frequently inherited tumors with an important genetic heterogeneity, with SDHB mutations being the most frequently associated with a metastatic disease." (PMID 32206105, 2020). "SDHB mutations have been linked to more aggressive tumor behavior, and are more likely to present with metastatic disease than patients with sporadic PHEOs/PGLs." (PMID 32862332, 2020). "PGLs with underlying SDHB mutations are associated with a higher risk of aggressive behavior, development of metastatic disease, and ultimately, death." (PMID 30106970, 2018). "Those with SDHB gene mutations ought to be aggressively followed given the high risk of metastatic disease." (PMID 28752085, 2017). "SDHB mutation carriers require lifelong biochemical and clinical surveillance due to these variations in presentation and the considerable risk of metastatic disease." (PMID 27896548, 2017). "The reported rate varies but it appears that PGLs associated with the SDHB germline mutation carries a significantly higher rate of a more aggressive behaviour locally and developing metastatic disease." (PMID 27535829, 2016). "Although our patient’s genetic testing results came back as negative, around 40–63% of patients with PUB carry a germline mutation and most commonly the SDHB subunit gene, which requires them to be followed up lifelong because of the increased risk of developing metastatic disease." (PMID 39810845, 2025). "Specifically, the detection of SDHB-related tumors indicates an increased risk of metastatic disease, which may impact decisions regarding functional imaging in patients with high suspicion of metastasis and influence targeted treatment strategies." (PMID 39735644, 2024). "SDHB pathogenic variant correlated with both recurrent and metastatic disease (p = 0.006)." (PMID 38849646, 2024). "SSTR2 expression was independently associated with SDHB/SDHx mutations and metastatic disease." (PMID 36946182, 2023). "An open adrenalectomy approach may be justified in patients with SDHB mutations due to the higher rate of metastatic disease in this group." (PMID 38155946, 2023).
metastatic disease (continued). "SDHB germline variants are most notably associated with the highest morbidity and mortality, commonly developing extra-adrenal sympathetic paragangliomas with the greatest risk for metastatic disease." (PMID 35685436, 2022). "Metastatic disease can occur in 12% of pediatric patients, in general, but may be up to 70% among SDHB mutation carriers, the second most commonly mutated gene in pediatric PPGL after VHL." (PMID 35903274, 2022). "SDHB mutation is known to correlate with metastatic disease, which is supported by our results." (PMID 34356532, 2021). "In 50% of patients with metastatic disease, a mutation in the SDHB gene was found." (PMID 33081307, 2020). "SDHB mutation carriers are reported to develop metastatic PGL more frequently and patients with metastatic disease associated with SDHB variants are reported to have a poor 5-year survival rate compared to patients with metastatic disease associated with other causative genes." (PMID 30658386, 2019). "There may, however, be a selection bias related to the high proportion of patients presenting with metastatic disease or known SDHB mutation." (PMID 27535829, 2016). "Furthermore, in childhood and adolescence the incidence of PHEO/PGL is rare; however, when metastatic disease is diagnosed in these age groups, these patients have a high probability of having SDHB mutations." (PMID 25048685, 2014). "Notably, loss of SDHB expression in metastatic tumors correlated with longer overall survival, suggesting that SDHB, combined with Ki-67%, may serve as a prognostic marker in metastatic SI-NETs." (PMID 41458541, 2025). "Moreover, the type of SDHB pathogenic variants may also be useful to indicate the potential risk for metastatic disease development." (PMID 38155946, 2023). "Given the higher risk for metastatic disease in patients with SDHB PVs and reported cases of early-onset of disease during childhood, it is proposed to start screening at age 6–10 for asymptomatic SDHB PV carriers and at age 10–15 for carriers of PVs in SDHA, SDHC, and SDHD genes." (PMID 37435466, 2022). "In addition, the mutations of succinate dehydrogenase B (SDHB) may lead to metastatic disease in at least 40% affected patients." (PMID 35932074, 2022). "Thus, young age and metastatic disease are both factors for SDHB mutation." (PMID 31372201, 2019). "Somatic variants in the TERT promoter were associated with aggressive tumor features, such as extra-adrenal location, germline SDHB PVs, and metastatic disease." (PMID 42155081, 2026). "Sensitivity analyses excluding studies with a mean time = 0 months (ie, metastatic disease at diagnosis) were performed for SDHB and SDHD." (PMID 41183483, 2026). "Our comprehensive multi-omic analysis of SDHB-mutant PCPG therefore identifies features of metastatic disease and treatment response, expanding our understanding of these rare neuroendocrine tumours." (PMID 40097403, 2025). "This study aims to explore the potential predictive effects of MAML3 and MCM6 expression, in addition to known histopathological features, SDHB, S100, and the Ki-67 proliferation index, in forecasting metastatic disease in PCC and PGL." (PMID 40445576, 2025). "Our comprehensive multi-omic analysis of SDHB-mutant PCPG therefore identified features of metastatic disease and treatment response, expanding our understanding of these rare neuroendocrine tumours." (PMID 38978571, 2024). "This classification in cases such as SDHB-related tumors defines the prognosis of developing metastatic disease and can modify the conduct of treatment and surveillance." (PMID 39735644, 2024). "None of these patients exhibited extra-adrenal sympathetic paragangliomas or metastatic disease, as generally expected of the SDHB phenotype." (PMID 38473309, 2024).
metastatic disease (continued). "The algorithm for genetic testing did not fit in 3 out of the 24 patients with hereditary disease as we observed one case of metastatic disease (arteria renalis invasion) in a patient with a VHL mutation and positive SDHB staining in 2 SDHD-related PPGL." (PMID 37434651, 2023). "We cultured 62 PPGLs, including tumours with confirmed SDHB, SDHC and SDHD variants, as well as several metastatic tumours." (PMID 36178902, 2022). "In total, 18 patients suffered from metastatic disease; germline mutations in SDHA, SDHB and SDHC were present in one patient each, while SDHD mutations were found in seven patients." (PMID 35171114, 2022). "More recently, it was shown that a combination of some GAPP parameters with a loss of SDHB IHC staining (M-GAPP), which is frequently observed in metastatic tumors, can better predict the metastatic potential of PPGLs." (PMID 34833055, 2021). "In particular, SDH subunit B (SDHB)-mutated PHEO/PGL is associated with a more aggressive tumor behavior and higher rates of metastatic disease when compared to all other PHEO/PGL cases." (PMID 34359671, 2021). "Numerous authors have demonstrated the variability in the SDHB gene, which leads to metastatic disease in 40% or more of patients." (PMID 33081307, 2020). "Compared with SDHA-related metastatic disease, the age at diagnosis among patients with SDHB-related metastatic disease was younger at 31 years old." (PMID 30854332, 2019). "From the patients that died of SDHB-related disease (n = 3), two already had proven metastatic disease at the time of diagnosis." (PMID 30658386, 2019). "In conclusion, SDHA-related metastatic PHEO/PGLs behave like SDHB-related metastatic disease, showing aggressive behavior, similar imaging and biochemical phenotypes, and suboptimal responses to conventional treatments." (PMID 30854332, 2019). "However, 123I-MIBG scintigraphy has shown reduced sensitivity in extra-adrenal, multiple, or hereditary PGLs (52–75%) associated with von Hippel Lindau syndrome as well as SDHB-related PGLs and patients with metastatic disease in whom 123I-MIBG scintigraphy may underestimate the extent of disease." (PMID 31261748, 2019). "SDHB mutations are especially related to sporadic malignant PCC with poor prognosis, and up to 40% of patients with metastatic disease harbor mutations in this gene." (PMID 29768630, 2018). "For patients with metastatic disease, SDHB should be tested first as more than 40% of this mutation is related to metastatic PCC/PGL and 5.5% of PCC/PGL patients carried SDHB germline mutation." (PMID 30613466, 2018). "Receiver operating characteristic curves established 4.5 cm as the best value to dichotomize the primary SDHB-related PHEO/PGL in order to evaluate the development of metastatic disease and 5.5 cm as the best value for survival prediction." (PMID 25048685, 2014). "The primary outcome, rate of metastatic disease per 100 followed patient-years, did not include the SDHB variant as heterogeneity exceeded 75%." (PMID 41183483, 2026). "A funnel plot of the SDHB group showed some asymmetry in the distributions of studies, suggesting that smaller studies with lower rates of metastatic disease might be underreported or unpublished, indicating potential publication bias." (PMID 41183483, 2026). "Recent studies have shown that succinate can effectively differentiate asymptomatic SDHB variant carriers from non-carriers and identify individuals who have developed the disease, with succinate levels correlating with metastatic disease extent." (PMID 41026309, 2025). "A detailed retrospective study of 872 patients with SDHx PGVs found a much lower risk of metastatic disease at 4.2% (95% CI 1.1–7.2%) by age 60 in non-proband SDHB PGV carriers." (PMID 40063004, 2025). "The presence of a germline pathogenic variant in SDHB is a well-established risk factor for metastasis, although approximately half of patients with metastatic disease do not have a hereditary SDHB pathogenic variant." (PMID 40445576, 2025).
metastatic disease (continued). "In one of these patients, a somatic SDHB mutation was found, three patients had metastatic disease, and four did not have a hereditary phenotype based on clinical and anamnestic observations." (PMID 37434651, 2023). "The majority were head and neck paragangliomas, together with 16 non-head and neck PPGLs, including two SDHB-associated metastatic tumours." (PMID 36178902, 2022). "There are some caveats with interpreting risk of metastatic disease for carriers of SDHB PVs because the definition of metastatic PCC/PGL has not been consistent in the literature." (PMID 37435466, 2022). "It has only been recently clarified that the association of cluster 1 mutations with metastatic disease is independent of the presence of SDHB mutations." (PMID 35201450, 2021). "This explains the significant correlation of high 3MT levels with metastatic disease; however, these can also present in metastasizing PPGLs in the absence of SDHB mutations." (PMID 34833055, 2021). "Metastatic disease is one of the features that indicates likelihood of a hereditary cause, and it is recommended that patients with malignant PCC should undergo genetic testing for SDHB, SDHC, SDHD, VHL and MAX." (PMID 29768630, 2018). "No clear associations between the occurrence of metastatic disease and genetic factors such as SDHB mutation type, or clinical factors such as age of the patient, size of the initial tumour or location of the initial tumour, were found." (PMID 29951630, 2018). "Similarly, the risk ratio of metastatic disease for SDHB compared with no genetic variant identified increased by 0.0544% per publication year (P = <.0001)." (PMID 41183483, 2026). "Interestingly, the authors showed that SSTR2 positivity was not only significantly associated with SDHB-and SDHx-related PPGLs, but with metastatic disease regardless of SDHB/SDHx mutation status." (PMID 38543140, 2024). "Moreover, SSTR2 expression is associated with metastatic disease independent of SDHB/SDHx mutation status." (PMID 36946182, 2023). "Moreover, SSTR2 expression was significantly associated with metastatic disease independent of SDHB/SDHx mutation status (P < .001)." (PMID 36946182, 2023). "Mutations occurring in the SDHB gene are more frequently associated with metastatic spread, but recent evidences showed that the presence of SDHB mutations did not correlate with the prognosis in patient with a metastatic disease." (PMID 34227051, 2022). "In addition, regardless of SDHB mutation status, tumor size has also been shown to be related to developing metastatic disease." (PMID 25048685, 2014). "In contrast, they found 100% of cases were due to an SDHx PGV (six SDHB and four SDHD), 70% had catecholamine excess and 60% eventually developed metastatic disease." (PMID 40063004, 2025). "This study aims to investigate the potential predictive effect of known histopathological features in PCC/PGL, alongside SDHB, S100, Ki-67 proliferation index, and the expression of MAML3 and MCM6 in predicting metastatic disease." (PMID 40445576, 2025). "To date, the NGS study of the tumor is only performed in research clinics for malignant, already metastatic tumors; in routine surgeries, molecular characterization, when there is any, involves only immunohistochemical analysis for SDHA and SDHB proteins." (PMID 39457697, 2024). "Therefore, patients suspected of heritable HNPGLs should undergo genetic analysis first at the SDHD and SDHB loci, whilst if metastatic tumors or multiple abdominal paragangliomas are found without any familial presentation, the presence of SDHB mutations should be tested first." (PMID 34072806, 2021). "Additionally, significant numbers of SDHB-affected patients harbor germ line SDHB mutations and suffer from a particularly aggressive form of malignant PPGL, whereas other family members with identical SDH mutations remain free of metastatic disease (see modifier genes above and mev-1 below)." (PMID 32859697, 2020).
metastatic disease (continued). "While mutations of SDHD are associated predominantly with HN-PGL, frequently multifocal and generally non-metastatic,SDHB mutation carriers frequently present with PCCs and extra-adrenal paragangliomas, and mutations of SDHB are more often found in patients with aggressive, metastatic disease." (PMID 19368708, 2009). "In our analyses of risk rate not adjusted for time, we found a significantly increased risk of metastatic disease in patients with pathogenic germline variants in SDHA, SDHB, SDHC, TMEM127, MAX, and FH compared to those with no identified pathogenic variant." (PMID 41183483, 2026). "A 2012 meta-analysis estimated the pooled incidence of metastatic disease in SDHB carriers (with and without appreciable disease) at 17% and in SDHD carriers at 8%." (PMID 40063004, 2025). "No mutations were detected in the genetic tests for SDHB and SDHD performed in patients with bilateral or metastatic disease." (PMID 38664798, 2024). "We found a unique association between a SDHB pathogenic variant and a VUS of MLH1 in a patient with PHEO diagnosed at 36 years old; he did not develop metastatic disease at 7 years of follow‐up." (PMID 39673085, 2024). "Especially SDHB-mutation carriers have higher risk of developing a metastatic disease and shorter survival than patients with a malignant PPGL, but without SDHB mutations." (PMID 34181326, 2021). "Two patients with SDHB mutations and one patient with SDHD mutation were characterized by metastatic tumors but no SDHA variants were detected." (PMID 33391357, 2020). "SDHB-mutation carriers have higher risk of developing a metastatic disease and shorter survival than patients with a malignant PGL/PCC but without SDHB mutations." (PMID 31372201, 2019). "In our cohort, two out of three PHEO with metastatic disease had negative SDHB immunostaining and noradrenergic phenotype, but we could not identify a pathogenic SDHx gene mutation." (PMID 37434651, 2023). "We next tested the hypothesis that EPAS1 activity is significantly different in SDHB-null metastatic tumors vs. those annotated as “non-malignant”." (PMID 31234811, 2019).